ENSG00000288591 (novel protein)
Gene: Protein-coding gene on chromosome 12 (64,759,496 to 64,977,509, forward strand). Ensembl gene ENSG00000288591.
Genetic constraint (gnomAD): Missense variants: 677 observed, 828.08 expected, observed/expected ratio (o/e) 0.82, 90% interval 0.77 to 0.87. Synonymous variants: 251 observed, 312.69 expected, observed/expected ratio (o/e) 0.8, 90% interval 0.72 to 0.89.